XKR4 (XK related 4)
Description:
[XK-related protein 4, processed form]: Phospholipid scramblase that promotes phosphatidylserine exposure on apoptotic cell surface. Phosphatidylserine is a specific marker only present at the surface of apoptotic cells and acts as a specific signal for engulfment.
Synonyms: hXKR4; KIAA1889; XRG4
Tractability: Antibody: UniProt places it where antibodies can reach, with medium confidence; UniProt predicts a signal peptide or a membrane-spanning region; its Gene Ontology location is reachable by antibodies, with medium confidence. PROTAC: its protein half-life has been measured.
Gene: Protein-coding gene on chromosome 8 (55,102,028 to 55,542,054, forward strand). Ensembl gene ENSG00000206579.
Subcellular location: Cell membrane
Subcellular location (Human Protein Atlas): Vesicles; Golgi apparatus; Nucleoli
Gene Ontology:
Biological process: apoptotic process involved in development; engulfment of apoptotic cell; phosphatidylserine exposure on apoptotic cell surface
Cellular component: plasma membrane; membrane
Genetic constraint (gnomAD): Loss-of-function variants: 12 observed, 52.3 expected, observed/expected ratio (o/e) 0.23, 90% interval 0.15 to 0.37. The upper end of that interval is the gene's LOEUF score, 0.37, which puts it in group 1 of 6, group 1 being the genes least tolerant of losing a copy. Missense variants: 799 observed, 842.45 expected, observed/expected ratio (o/e) 0.95, 90% interval 0.89 to 1.01. Synonymous variants: 354 observed, 344.69 expected, observed/expected ratio (o/e) 1.03, 90% interval 0.94 to 1.12.
Homologues: Orthologues: chimpanzee XKR4 (99% identical), macaque XKR4 (99% identical), rabbit XKR4 (98% identical), dog XKR4 (96% identical), rat Xkr4 (96% identical), mouse Xkr4 (96% identical), pig XKR4 (95% identical), tropical clawed frog xkr4 (83% identical), guinea pig XKR4 (82% identical), zebrafish xkr4 (75% identical). Paralogues in human: XKR6 (44% identical), XKR7 (43% identical), XKR8 (18% identical), XKR5 (17% identical), XKR9 (15% identical).
Diseases named in the same sentence as XKR4 in open-access papers:
XKR4 is named in the same sentence as 10 diseases in open-access papers, as found by Europe PMC text mining. Sharing a sentence is not in itself a finding about the gene and the disease. The quoted sentences say what the papers report.
attention deficit-hyperactivity disorder (2 papers, 2012 to 2017). A disorder characterized by a marked pattern of inattention and/or hyperactivity-impulsivity that is inconsistent with developmental level and clearly interferes with functioning in at least two settings (e.g. at home and at school). "A single-nucleotide polymorphism (SNP) of the XKR4 gene has been linked to Attention-Deficit/Hyperactivity Disorder (ADHD)." (PMID 29311829, 2017). "This study investigates the effects of XKR4, a recently identified candidate gene for Attention-Deficit/Hyperactivity Disorder (ADHD), birth weight, and their interaction on brain volume in ADHD." (PMID 24179763, 2012).
substance abuse (2 papers, 2012 to 2024). The use of a drug for a reason other than which it was intended or in a manner or in quantities other than directed. "Finally, the XKR4-gene itself has been associated with substance abuse, and a SNP slightly upstream from XKR4 has been associated with response to antipsychotic medication, underscoring its potential relevance to psychiatric phenotypes." (PMID 24179763, 2012). "Association analyses of age-at-onset, number of mood episodes, and presence of psychosis, substance abuse and/or suicidal ideation suggested modest contributions of genes such as RTN4, XKR4, NRXN1, NRG1/3 and GRK5 to disease characteristics." (PMID 38570518, 2024).
colorectal carcinoma (1 paper, 2018). A malignant epithelial neoplasm that arises from the colon or rectum and invades through the muscularis mucosa into the submucosa. "Together, the potential combined effect of modulation of macrophages via efferocytosis and T-cells via PD-L1 expression, prime a favorable tumor-microenvironment raising the importance of dysregulation of CBL, CBLB, XKR4 and ANO5 in colorectal carcinoma." (PMID 30429477, 2018).
sexual precocity (1 paper, 2018). "It should be noted that the ESRRG and XKR4 genes can also influence lipid metabolism demonstrating the importance of these genes for sexual precocity in Nellore heifers since genes that affect fat deposition and, consequently, body condition play an important role in Zebu breeding." (PMID 29293544, 2018).
carcinoma (1 paper, 2018). A malignant tumor arising from epithelial cells.
XKR4 also shares sentences with these, for which no sentence is quoted: bipolar disorder (1 paper); coronary artery disease (1); psychosis (1); schizophrenia (1); tumor (1).